ADAMTS13 (ADAM metallopeptidase with thrombospondin type 1 motif 13)
Diseases named in the same sentence as ADAMTS13 in open-access papers (continued):
Sharing a sentence is not in itself a finding about the gene and the disease.
liver fibrosis (4 papers, 2011 to 2023). "Coagulation factors, including FVIII and other molecules involved in hemostasis, such as VWF, have been implicated in the progression of liver fibrosis, while factors such as ADAMTS13 have shown potential in reducing fibrogenesis." (PMID 37443746, 2023). "Additionally, negative association was observed between plasma ADAMTS13: AC and liver fibrosis stage in the present study, consistent with prior observations that plasma ADAMTS13: AC was related to developing various complications and survival time in patients with liver cirrhosis." (PMID 30976044, 2019).
myocardial ischemia (4 papers, 2016 to 2025). A disorder of cardiac function caused by insufficient blood flow to the muscle tissue of the heart. "Studies in cerebral and myocardial ischemia/reperfusion injury demonstrated larger infarct sizes and increased infiltration of neutrophils and pro-inflammatory cytokines in ADAMTS13-deficient mice, effects that were attenuated by recombinant ADAMTS13 administration." (PMID 41009700, 2025). "A myocardial ischemia/reperfusion study in ADAMTS-13-knockout mice showed that infusion of recombinant ADAMTS-13 substantially reduced myocardial apoptosis, troponin-I release, and resulted in a 9-fold reduction in the number of neutrophils infiltrating the ischemic zone." (PMID 33096906, 2020).
angina (3 papers, 2019 to 2020). "In unstable angina patients ADAMTS13 were lower compared with stable angina and showed an inverse correlation between ADAMTS13 and VWF." (PMID 32095288, 2020). "In unstable angina (UA) patients with the tendency of thrombogenicity increases if the proportion between VWF and ADAMTS13 changes significantly." (PMID 32095288, 2020). "On the other hand, the plasma levels of ADAMTS-13 were significantly lower in patients with acute MI (799 ± 29 mU/mL) than in patients with stable angina (996 ± 31 mU/mL) or patients without hemodynamically significant stenosis or vasospasm (967 ± 31 mU/mL)." (PMID 33096906, 2020). "The enzymatic activity of ADAMTS-13 was also lower in patients with acute MI (768 ± 27 mU/mL) than in patients with stable angina (893 ± 27 mU/mL) or patients without hemodynamically significant stenosis or vasospasm (936 ± 29 mU/mL)." (PMID 33096906, 2020).
aortic stenosis (3 papers, 2021 to 2024). Aortic valve stenosis is a aortic valve disease caused by the incomplete opening of the aortic valve. "As previously demonstrated, increased shear stress during aortic stenosis (AS) is associated with a loss of the high molecular weight (HMW) of the von Willebrand factor (vWF) due to proteolysis of vWF multimers by the metalloproteinase ADAMTS13." (PMID 34847152, 2021). "Shear stress in conditions such as aortic stenosis unfolds the von Willebrand factor multimers, exposing their A2 domain, which allows the enzyme ADAMTS13 to cleave them, reducing the high-molecular-weight multimers essential for platelet adhesion." (PMID 39803034, 2024). "In patients with aortic stenosis, the shear stress generated by the narrowed aortic valve fragments the high-molecular-weight multimers (HMWM) of von Willebrand factor through the action of the ADAMTS13 enzyme, resulting in their proteolysis and consequently a deficiency of these multimers." (PMID 39803034, 2024).
chronic hepatitis B (3 papers, 2019 to 2021). "The ADAMTS13 (a disintegrin and metalloproteinase with a thrombospondin motif repeats 13) is a key factor involved in coagulation process and plays a vital role in the progression and prognosis of chronic hepatitis B (CHB) patients with antiviral treatment." (PMID 32793509, 2020).
chronic liver failure (3 papers, 2023 to 2025). Liver failure that develops slowly and gradually for some time, possibly for years, often as the result of cirrhosis, or malnutrition. "The chronic liver failure consortium (CLIF-C) ACLF score, MELD score, VWF:Ag level, and VWF:Ag/ADAMTS13:AC level in the survival subgroup of the post-ACLF group were lower than those of the mortality subgroup (p < 0.05 for all)." (PMID 36829443, 2023).
colorectal cancer (3 papers, 2019 to 2025). A primary or metastatic malignant neoplasm that affects the colon or rectum. "In line with this, reduced ADAMTS13 expression has been linked to advanced disease stages in malignancies such as colorectal cancer." (PMID 41211185, 2025). "In the univariate Cox hazard analysis, ADAMTS13 emerged as a significant risk factor, demonstrating a strong predictive role in patients with colorectal cancer (CRC)." (PMID 37691826, 2023). "This consolidated the literature data on an association of increased VWF and/or decreased ADAMTS‐13 with worse survival probability in colorectal cancer, cancer of the head and neck, lung cancer, and in Waldenström's macroglobulinemia." (PMID 31294335, 2019). "Median values for ADAMTS‐13 were lowest in lung and colorectal cancers but within normal range of 40%‐130% for most patients." (PMID 31294335, 2019).
dengue (3 papers, 2012 to 2019). "In conclusion, severe dengue is associated with exocytosis of WPBs with consumption of VWF and low ADAMTS-13 activity levels." (PMID 22563509, 2012). "In support of this hypothesis, in a study of pediatric patients with severe dengue, ADAMTS13 activity was noted to be lower than normal, presumably secondary to consumption." (PMID 29727450, 2018).
Depression (3 papers, 2019 to 2025). "Eligibility criteria included (a) age > 18 years, (b) ADAMTS13‐deficient TTP, (c) enrolled in the Oklahoma Registry, and (d) moderate/major depression on either the Beck Depression Inventory II or Patient Health Questionnaire from 2004 to 2012." (PMID 31768419, 2019). "Depression and anxiety scores were not statistically associated with number of TTP episodes, presence of neurological symptoms, number of TPE procedures, ADAMTS13 activity during remission, and abnormal MRI." (PMID 37568558, 2023).
Hepatitis (3 papers, 2021 to 2025). Inflammation of the liver. "Extensive work-ups for ADAMTS13, HIV, and hepatitis were negative." (PMID 40873821, 2025).
hepatocellular carcinoma (3 papers, 2019 to 2025). A malignant tumor that arises from hepatocytes. "In 2019, Takaya and colleagues reported that an imbalance of ADAMTS13 with its substrate, von Willebrand factor, could be used as a detection marker for diagnosis of hepatocellular carcinoma." (PMID 35011462, 2021). "The discrepant results obtained from the TCGA and GEO databases regarding VWF and ADAMTS13 highlight the imbalance between VWF and ADAMTS13 in hepatocellular carcinoma (HCC)." (PMID 40699668, 2025).
liver dysfunction (3 papers, 2021 to 2024). "ADAMTS13 antigen levels were also reduced and >80% of patients with ADAMTS13 activity levels <30% had albumin levels below normal reference range, thus liver dysfunction may explain a low ADAMTS13 activity in these patients." (PMID 33709050, 2021). "Diminished ADAMTS-13 levels are probably attributed to elevated VWF levels, leading to consumption of ADAMTS-13, while liver dysfunction is an adding factor." (PMID 38399555, 2024). "A previous study reported a decrease of ADAMTS13-Act in cirrhotic patients (n = 90) with CTP stages B and C (but not CTP-A) and similar results were reported among ACLD patients with severe impairment of liver dysfunction." (PMID 37605068, 2023). "Surprisingly, ADAMTS13-Act was not related to VWF biomarkers or the VWF-Ag/-A ratio, and also similar between different stages of PH and liver dysfunction in our cohort of clinically stable ACLD patients and liver-healthy controls, which add important data to the controversy on ADAMTS13-Act in ACLD." (PMID 37605068, 2023).
liver failure (3 papers, 2018 to 2023). A liver disease characterized by the liver losing or has lost all of its function. "Accordingly, vWF-Ag/ADAMTS13-AC “high” patients might benefit from detailed monitoring to detect postoperative liver failure." (PMID 30429491, 2018). "Nevertheless, most of them lack sufficient evaluation of ADAMTS13-AC and its predictive potential to detect patients who might be affected by post-hepatectomy liver failure." (PMID 30429491, 2018). "Our group further evaluated changes in ADAMTS-13/VWF in patients with advanced chronic liver disease in relation to markers of endotoxemia such as LPS, confirming the strong association between decreased ADAMTS-13/VWF, chronic low-grade inflammation, and risk of liver failure." (PMID 37443746, 2023).
lung carcinoma (3 papers, 2019 to 2022). "The increase of VWF and the decrease of ADAMTS-13 promote the invasion and metastasis of lung cancer." (PMID 36181128, 2022).
metastatic cancer (3 papers, 2018 to 2021). A carcinoma which has spread from the original site of growth to another anatomic site. "In the present cohort of patients with cancer ADAMTS‐13 was lowest in patients with lung, colorectal, and metastatic cancers but within the normal range in most individuals." (PMID 31294335, 2019). "On the contrary, ADAMTS13 levels are found to be low in patients with metastatic cancer and GiTMA, suggesting that gemcitabine induces the formation of antibody against ADAMTS13 enzyme." (PMID 29329518, 2018). "While ADAM28 acts as a semi-functional homologue of ADAMTS-13 in cleaving circulating VWF, it is interesting to note that while ADAMTS-13 levels have been shown to decrease in a range of metastatic cancer including breast, ADAM28 expression is correlated with advanced disseminated disease." (PMID 33571850, 2021).
multiple sclerosis (3 papers, 2020 to 2025). A progressive autoimmune disorder affecting the central nervous system resulting in demyelination. "Three patients were treated with alemtuzumab for multiple sclerosis, two of which reported ADAMTS13 activity levels < 10 % with inhibitors." (PMID 39883995, 2025). "Reduced ADAMTS13 levels in plasma have been detected in multiple sclerosis (MS) patients." (PMID 32075652, 2020).
paroxysmal nocturnal hemoglobinuria (3 papers, 2021 to 2025). Paroxysmal nocturnal hemoglobinuria (PNH) is an acquired clonal hematopoietic stem cell disorder characterized by corpuscular hemolytic anemia, bone marrow failure and frequent thrombotic events. "Further investigations excluded other causes of hemolysis (absence of schistocytes, normal ADAMTS13 levels, absence of paroxysmal nocturnal hemoglobinuria -PNH- clones) and confirmed DAT positivity." (PMID 33672504, 2021). "The screening results were notable for normal coagulation, normal ADAMTS13 activity and inhibitor levels, negative direct and indirect Coombs tests, and the absence of paroxysmal nocturnal hemoglobinuria (PNH) clones." (PMID 40717883, 2025).
pneumonia (3 papers, 2017 to 2024). An acute, acute and chronic, or chronic inflammation focally or diffusely affecting the lung parenchyma, caused by an infection in one or both of the lungs (by bacteria, viruses, fungi, or mycoplasma.). "A procoagulant imbalance has also been observed in patients with nosocomial pneumonia; in particular, the VWF/ADAMTS13 ratio was higher in patients with pneumonia than in healthy subjects." (PMID 39408067, 2024). "In this comparison, syndecan-1 and heparan sulfate plasma concentrations are significantly higher and ADAMTS13 significantly lower in patients progressing from pneumonia to severe pulmonary failure (ARDS)." (PMID 36776845, 2023). "In conclusion, we demonstrate an important role for ADAMTS-13 in the innate immune response against A. fumigatus induced pneumonia." (PMID 28775254, 2017).
prediabetes (3 papers, 2017 to 2021). "The findings that the association was robust to the adjustment for baseline fasting glucose and insulin levels and that ADAMTS13 activity was also associated with incident prediabetes limit the possibility of reverse causation." (PMID 27787621, 2017). "Furthermore, ADAMTS13 activity was associated with the incidence of prediabetes among participants with normoglycaemia at baseline." (PMID 27787621, 2017). "ADAMTS13 activity was also associated with incident prediabetes (defined on the basis of both fasting and non-fasting blood glucose) after adjustment for known risk factors (HR 1.11 [95% CI 1.03, 1.19]), while the VWF antigen level was not." (PMID 27787621, 2017).
septic shock (3 papers, 2017 to 2021). Shock caused by infection; frequently caused by gram negative bacteria, although some cases have been caused by other bacteria, viruses, fungi, and protozoa; characterized by fever, chills, tachycardia, tachypnea, and hypotension. "A prospective study on 72 septic shock patients showed that low ADAMTS13 activity correlated well to high interleukin-6 levels." (PMID 34819564, 2021). "In this prospective study, septic shock was associated with activation of pro-coagulant pathways such as vWF:Ag and ultra-large VWF multimers and consumption of anti-coagulant factors such as ATIII, protein C, and ADAMTS13 activities." (PMID 32122366, 2020).
subarachnoid hemorrhage (3 papers, 2020 to 2025). A serious neurological disorder characterized by intracranial hemorrhage into the subarachnoid space. "NGAL exhibits a significant association with macrovascular vasospasm during the early phase of subarachnoid hemorrhage (SAH), whereas ADAMTS13 appears to be more closely related to this condition during the late phase of SAH." (PMID 37446186, 2023).
acute coronary syndrome (2 papers, 2023 to 2024). Signs and symptoms related to acute ischemia of the myocardium secondary to coronary artery disease. "Furthermore, the antithrombotic protein ADAMTS13 was shown to be decreased and to have a strong inverse relation with cardiac injuries like acute coronary syndrome." (PMID 39620151, 2024).
Anxiety (2 papers, 2023 to 2026). Intense feelings of nervousness, tension, or panic often arise in response to interpersonal stresses. "Advanced age was associated with lower anxiety scores, and previous ADAMTS-13 relapses led to lower anxiety scores." (PMID 41552747, 2026). "Lastly, previous ADAMTS-13 relapses were associated with less severe anxiety, possibly following a growing familiarization of patients with their disease, with the finding that pre-emptive treatment is efficient in preventing clinical relapses." (PMID 41552747, 2026). "Accordingly, severe anxiety was associated with younger age and no previous ADAMTS-13 relapses; furthermore, caplacizumab administration led to decreased risk of severe anxiety." (PMID 41552747, 2026).
cerebral microbleeds (2 papers, 2019 to 2021). Cerebral microbleeds are a group of pathological processes affecting the small arteries, arterioles, capillaries and venules of the brain, as detected by brain imaging techniques. "Interestingly, decreased ADAMTS13, which exerts an inhibitory function on vWF activity, was detected in MS patients and in particular in those with cerebral microbleeds." (PMID 31068896, 2019).
chronic heart failure (2 papers, 2022 to 2023). "In patients with chronic heart failure, a high ADAMTS13/vWF-ratio is associated with a lower risk of clinical events." (PMID 36009558, 2022).
complement factor H deficiency (2 papers, 2011 to 2014). "These conditions might cause acquired TTP, HUS, or other TMAs, or might be a trigger in individuals with genetic predisposition to ADAMTS-13 or complement factor H deficiency." (PMID 25386342, 2014).
diabetic retinopathy (2 papers, 2025). "Regulation of retinal ADAMTS13 expression was also studied in a rat model of diabetic retinopathy." (PMID 39851513, 2025).
dyslipidemia (2 papers, 2021 to 2022). "In short, high ADAMTS13 correlates to the components of metabolic syndrome, but low ADAMTS13 carries a significant cardiovascular risk." (PMID 34819564, 2021). "Thus, the liver cells in patients with dyslipidemia could be damaged by fat deposition, and production of ADAMTS13 could be decreased in patients with central RVO." (PMID 36137144, 2022). "ADAMTS13 activity was significantly lower in central RVO than in branch RVO at baseline, but the number of dyslipidemia cases was significantly higher in central RVO." (PMID 36137144, 2022). "However, the correlations between ADAMTS13 and the components of metabolic syndrome were not only observed in non-CKD population but also in our HD patients." (PMID 34819564, 2021).
hemorrhage (2 papers, 2020 to 2023). Loss of blood from the vascular compartment to the exterior or into nonvascular body space as a result of rupture or severance of the blood vessels. "In animal studies, absence of ADAMTS13 exacerbates outcomes of ischemia or reperfusion injury, while injecting recombinant ADAMTS13 reduces rt-PA-associated hemorrhage." (PMID 32849241, 2020). "Plasma VWF levels are elevated in diseases associated with the blood-brain barrier disruption, while whether low ADAMTS13 level is associated with more rt-PA-induced hemorrhage is unknown." (PMID 32849241, 2020). "When stratified according to modified Fisher grade, patients with high-grade bleeding (mFisher score = III-IV) had a significantly higher level of ADAMTS13 at D1 and D3 compared with that of patients with low-grade hemorrhage (mFisher score = I-II)." (PMID 37446186, 2023).
hepatic veno-occlusive disease (2 papers, 2015 to 2023). Hepatic veno-occlusive disease (hepatic VOD) is a condition resulting from toxic injury to the hepatic sinusoidal capillaries that leads to obstruction of the small hepatic veins. "We have previously reported that plasma ADAMTS13 activity (ADAMTS13:AC) was reduced in patients with SOS, formerly called hepatic veno-occlusive disease (VOD), after hematopoietic stem cell transplantation (SCT)." (PMID 26580395, 2015).
hepatitis C (2 papers, 2018 to 2022). "Some previous studies reported that interferon and direct acting antivirals (DAAs) helped in recovery from the imbalance between ADAMTS13 enzyme and VWF substrate and high Et levels in patients with LC and hepatitis C." (PMID 35407443, 2022). "Further workup was undertaken for TMA, and apart from mildly elevated lactate dehydrogenase of 380 (normal <243), active hepatitis C, and slightly low ADAMTS-13 (55%), there was no other laboratory evidence of TMA." (PMID 29435466, 2018).
Hypercholesterolemia (2 papers, 2022 to 2024). An increased concentration of cholesterol in the blood. "However, studies have indicated that high oxidative stress, which occurs in hypercholesterolemia and MI, can impair ADAMTS13 activity and removal of VWF from the endothelial surface, providing an explanation for the effects of additional enzyme." (PMID 38693516, 2024).
Hyperglycemia (2 papers, 2016 to 2021). An increased concentration of glucose in the blood. "According to these 2 studies and ours, the associations between ADAMTS13 and hyperglycemia, hypertriglyceridemia and low HDL seem to be consistent in both non-CKD and HD patients." (PMID 34819564, 2021).
hyperlipidemia (2 papers, 2018 to 2022). "Moreover, interferences in the assay measuring ADAMTS13 can occur from a high concentration of von Willebrand factor (vWF), hyperlipidemia, hemolysis with plasma free Hb > 2 g/L, and hyperbilirubinemia, and cleavage by other proteases can even complicate identification of TTP." (PMID 29855343, 2018).
Hypofibrinogenemia (2 papers, 2021 to 2023). Decreased concentration of fibrinogen in the blood. "Hyperfibrinolysis may be the primary mechanism responsible for hypofibrinogenemia and may also participate in ADAMTS13 degradation." (PMID 34343182, 2021).
immune thrombocytopenia (2 papers, 2018 to 2022). "With regard to the importance of a differential diagnosis of thrombotic microangiopathic disorders, we present a case of inherited ADAMTS13 deficiency with initial clinical features that mimicked a recurrent immune thrombocytopenic purpura (ITP)." (PMID 29357939, 2018).